IL27 (interleukin 27)
Diseases named in the same sentence as IL27 in open-access papers (continued):
Sharing a sentence is not in itself a finding about the gene and the disease.
coronary artery disease (14 papers, 2012 to 2025). "A second study in 402 patients referred for coronary angiography (52% of whom had evidence of coronary artery disease) has shown that circulating IL-27 levels > 25 ng/mL have a 1.8-fold higher risk of future cardiovascular events." (PMID 41302192, 2025). "IL-27 is one of the cytokines elevated in patients with coronary artery disease, although it is unclear if IL-27 plays a pathogenic or protective role in the cardiovascular system." (PMID 35251049, 2022). "Moreover, the mean level of IL-27 in the serum of the AMI and UA groups was significantly higher than that of the control, which indicates that the higher serum level of IL-27 was associated with the incidence of ischemic heart disease (IHD)." (PMID 31011288, 2019). "A recent prospective study in patients after myocardial infarction and in patients undergoing coronary angiography has also shown a prognostic role of IL-27 in patients with coronary artery disease." (PMID 41302192, 2025). "Mechanistically, IL-27 amplifies the pro-inflammatory cascade in coronary artery disease by increasing LDL-induced dendritic cell activation, which stimulates the release of inflammatory mediators that promote vascular injury." (PMID 39906735, 2024). "A prior study of human subjects with a spectrum of coronary artery disease showed IL-27 levels strongly, positively correlate with oxidized LDL cholesterol levels and the Gensini score (an index coronary atherosclerosis severity)." (PMID 25699211, 2015). "The study highlights the role of IL-27 in the pathogenesis of ischemic heart disease." (PMID 39844544, 2025). "According to a study, IL-27 was shown to be elevated in coronary artery disease (CAD), especially in patients with acute coronary syndrome (ACS)." (PMID 39844544, 2025). "Moreover, IL-27’s duality extends to ischemic heart disease, where elevated serum levels enhance immune cell activation during acute myocardial infarction while simultaneously reducing oxidative stress and stabilizing atherosclerotic plaques through STAT3 signaling." (PMID 39906735, 2024). "Interleukin-27 (IL-27) is an important cytokine in inflammatory diseases, including coronary artery disease (CAD)." (PMID 27174010, 2016). "Significantly decreased amounts of IL-35, IL-10 as well as TGF-β were observed in plasma of patients with coronary artery disease (CAD) with a concomitant elevation in plasma IL-12 and IL-27 levels." (PMID 29641433, 2018). "However, after adjusting for traditional risk factors and co-morbidities—including age, sex, chronic limb-threatening ischemia, coronary artery disease, cerebrovascular disease (CVD), diabetes, and smoking—IL-27 levels independently predicted only MACE." (PMID 41302192, 2025).
Crohn disease (14 papers, 2013 to 2025). A gastrointestinal disorder characterized by chronic inflammation involving all layers of the intestinal wall, noncaseating granulomas affecting the intestinal wall and regional lymph nodes, and transmural fibrosis. "Studies have shown that elevated IL-27 levels are closely associated with disease activity in Crohn’s disease (CD)." (PMID 39906735, 2024). "Other studies have indicated that the A allele of the IL-27 rs153109 polymorphism is associated with increased risk of Crohn’s disease and ulcerative colitis in a Korean population, while it is associated with resistance to Crohn’s disease in a Chinese Han population." (PMID 30268141, 2018). "IL-27 is positively associated with multiple inflammation indicators and may exert a proinflammatory profile by regulating Th17 cell differentiation in the development of Crohn's disease." (PMID 34744512, 2021). "In Crohn’s disease, IL-27 tends to exert pro-inflammatory effects by promoting Th1 differentiation and IFN-γ secretion, though it also has regulatory functions such as inducing IL-10 production." (PMID 39906735, 2024). "Elevated levels of IL-27 mRNA were also found in patients with active Crohn’s disease and an enhanced percentage of IL-27 immunoreactive cells in the gut mucosa in patients with active ulcerative colitis." (PMID 31949260, 2020). "in a study on 30 individuals with early-onset Crohn's disease found that the Colonic tissue gene expression of IL-27 was significantly lower than in 11 healthy controls." (PMID 30774807, 2018). "Increased expression of IL-27 in inflamed segments of the intestinal mucosa has been demonstrated in both Crohn’s disease and ulcerative colitis." (PMID 29118930, 2017). "Similarly, risk alleles for T1D, such as Interleukin 27 (IL-27), Interleukin 10 (IL-10), and interleukin-18 receptor 1 (IL18RA), have been found to prevent Crohn’s disease." (PMID 39350769, 2024). "In addition, in the mucosa and muscle tissues of patients with active ulcerative colitis and active Crohn’s disease, the number of cells that produce IL-27 was increased." (PMID 39766196, 2024). "We also found that sIL-27Rα levels were positively correlated with IL-27 levels (R = 0.27, P = 0.029), in accordance with similar observations in Crohn’s disease patients, suggesting that the interaction between IL-27 and sIL-27Rα may play critical role in aGVHD biology." (PMID 29985424, 2018).
hepatocellular carcinoma (14 papers, 2010 to 2025). A malignant tumor that arises from hepatocytes. "(2009), hepatoma cells and hepatocytes stimulated with IL-27 displayed sustained activation of STAT-1 and STAT-3, leading to an IFN-γ-like STAT-1-dependent response." (PMID 38720890, 2024). "This is in line with a study showing that IL-27 pretreatment of hepatocellular carcinoma cells resulted in lowered IL-2 production by anti-CD3/-CD28 activated T-lymphocytes." (PMID 37818353, 2023). "Solid tumor animal models and cellular experiments with bioinformatics research have demonstrated that blocking IL-27 signaling is beneficial for the treatment of hepatocellular carcinoma and renal cell carcinoma." (PMID 35058928, 2021). "We previously reported a function of IL-27 in hepatoma cells and primary hepatocytes and showed that IL-27 responses are not restricted to the classical immune cells." (PMID 20719000, 2010). "IL-27 was shown to exert Interferon-γ-like functions in hepatocytes/hepatoma cells and to contribute to the antiviral response in these cells." (PMID 20719000, 2010). "Additionally, IL-27 stimulation induces PD-L1 expression on several types of cancer cells including: prostate, lung, and hepatocellular carcinoma." (PMID 31681561, 2019). "However, in STAT1 gene-silenced hepatocellular carcinoma cells, IL-27 mediated expression of γ-fibrinogen, which is typically induced by IL-6." (PMID 28255204, 2017). "In addition, also human keratinocytes, astrocytes, and hepatocytes or hepatoma cells or THP-1 monocytic cells display increased HLA class I expression in response to IL-27." (PMID 27683036, 2016). "Similarly, IL-27 has antiviral activity in hepatoma cells and can induce the expression of IRF-1, guanylate binding protein 2 and MxA proteins that are involved in the antiviral response." (PMID 20719000, 2010). "Furthermore, IL-27 levels were also enhanced in patients with liver cirrhosis or hepatocellular carcinoma." (PMID 20719000, 2010). "Furthermore, IL-27 was recently reported to possess strong antitumor activity in a murine model of hepatocellular carcinoma." (PMID 20719000, 2010). "IL-27+ Bregs have been reported to be upregulated and associated with more aggressive diseases in patients with colorectal adenocarcinoma (CRC), liver metastases from CRC, hepatocellular carcinoma (HCC), and other solid tumors." (PMID 36618354, 2022). "Correlation among mediators (IL-6, IL-27, TNF-α, and VEGF) with STAT proteins at diverse clinical-pathologic stages of hepatocellular carcinoma (HCC) remains limited." (PMID 25908103, 2015). "Previous findings indicated that GP130 signaling, induced by IL-6 ligands, may switch-off the responsiveness to IL-27, through the induction of the suppressor of cytokine signaling, SOCS3, in human hepatocellular carcinoma cells." (PMID 29020964, 2017). "Recent data indicate that IL-6 may interfere with IL-27 functions due to the induction of SOCS3 expression, which inhibits IL-27-mediated STAT signaling, in hepatocellular carcinoma cells." (PMID 29020964, 2017). "Our present data fits to our previous observation that IL-27 does not regulate the STAT3-dependent acute-phase proteins γ-fibrinogen and hepcidin in hepatocytes and hepatoma cells." (PMID 20719000, 2010).
type 1 diabetes (13 papers, 2015 to 2025). "Most remarkably, we identify a common missense variant in IL27, associated with type 1 diabetes that results in decreased functional activity of the protein and reduced expression levels of downstream IRF1 and STAT1 in CD4+ T cells only." (PMID 28248954, 2017). "Genome-based approaches for identifying genetic polymorphisms associated with Type 1 diabetes (such as IL-2RA and CUX2) have revealed specific SNPs (such as PTPN22, IL-10, IL-27, and IL18RAP) with contrasting effects on the development of Type 1 diabetes." (PMID 38474087, 2024). "The aim of this study was to evaluate the concentration of sirtuin 1, visfatin, and IL-27 in relation to cardiovascular parameters and Hashimoto’s disease (HD) in young, asymptomatic women with type 1 diabetes mellitus (T1DM)." (PMID 34439776, 2021). "This selective sorting towards EV subspecies has been demonstrated in Type 1 diabetes in which MCP-1 was expressed in all sorts of EVs while IL-27 was solely expressed in apoptotic bodies." (PMID 33046133, 2020). "However, in another study, the risk alleles for type-1 diabetes such as PTPN22, interleukin (IL)-27, and IL-10 loci were shown to protect against CD." (PMID 30862129, 2019). "However, the contradictory effects of IL-27 have been reported in type 1 diabetes (T1D)." (PMID 32849596, 2020). "Conversely, the SNP rs3024505 within IL-10 and the rs4788084 locus near IL-27 and NURP1 genes exhibit protective roles against the onset of Type 1 diabetes." (PMID 38474087, 2024). "In type 1 diabetes, IL-27-MSC may activate IDO to expand Tregs in pancreatic lymph nodes, thereby inhibiting β-cell destruction by effector T cells, with TSG-6 potentially mitigating islet inflammation." (PMID 40642057, 2025). "Similarly, transcripts of candidate genes for type 2 diabetes (Blk, C2cd4a, C2cd4b, Cdkn2a, Hnf1a, Mtnr1b, Pou5f1, Slc30a8) and type 1 diabetes (Cd69, Il2, IL27) were not expressed in the brain." (PMID 39920851, 2025).
diabetes (12 papers, 2015 to 2025). "In streptozotocin (STZ)-induced models of diabetes, mice deficient in IL-27 signaling components (EBI3−/− or WSX-1−/−) developed more severe hyperglycemia and islet inflammation." (PMID 40804870, 2025). "IL-27 has gained increasing attention in diabetes research due to its complex immunomodulatory functions." (PMID 40804870, 2025). "Studies that used NOD mice as a disease model showed a pro-inflammatory role of IL-27 in diabetes development, but studies that selected streptozotocin to induce diabetes showed an anti-inflammatory role of IL-27 in diabetes pathogenesis." (PMID 38566992, 2024). "Transferring bone marrow (BM) cells from Rag1−/− NOD mice into IL-27−/− NOD mice upregulated the incidence of diabetes." (PMID 38566992, 2024). "It was found that IL-27 exerted a protective effect against diabetes by ameliorating STZ-induced hyperglycemia and islet inflammation." (PMID 37600722, 2023). "The role of IL-27 in diabetes is different from that in other autoimmune diseases or allergic inflammation." (PMID 34045653, 2021). "In the presence of diabetes, the basal secretion of IL-1β, IL-27, IL-33, and SDF-1 is augmented while that of IL-10, IL-12, and IL-8 was downregulated." (PMID 34566972, 2021). "Interestingly, Helicobacter pylori infection—particularly with the virulent CagA-positive strain—has been shown to suppress IL-27 production in T1D patients, pointing to a potential interaction between microbial exposure and cytokine regulation in diabetes." (PMID 40804870, 2025). "The addition of IL-27 reduced the incidence of diabetes and disease severity." (PMID 38566992, 2024). "While IL-27 levels are increased, IL-38 are significantly reduced in pre-diabetes." (PMID 38327565, 2024). "IL-27 gene polymorphisms (rs153109, rs34833, rs26528, rs17855750, rs181206, and rs40837) were not related to T1D risk in Brazil, and IL-27 genetic mutation did not correlate with gender, age at diagnosis of diabetes, and patients with pancreatic and extrapancreatic autoantibodies." (PMID 38566992, 2024). "This may contribute to different results of IL-27 in diabetes." (PMID 38566992, 2024). "Secretion of IL-27, IL-1Ra, IL-12, IL-33, IL-9, and SDF-1 was increased under diabetes conditions with increased Th9 polarization and increased expression of Cox-2 and IDO." (PMID 34566972, 2021). "The intervention with VD3 and/or RSV alleviated metabolic abnormalities induced by type 2 diabetes mellitus (T2DM), resulting in elevated levels of the anti-inflammatory factor IL-27 and reduced levels of the pro-inflammatory factor IL-23 in the hippocampus of rats." (PMID 41049367, 2025). "On the other hand, NOD mice lacking IL-27 or IL-27Rα completely resist diabetes development." (PMID 41027725, 2025). "Furthermore, experiments, however, will be required to directly confirm if IL-27 plays critical roles in developing diabetes after β cell injury in the absence of Lnk." (PMID 41027725, 2025). "Co-transfer of CD4+ and CD8+ T cells from NOD mice into Rag1−/− NOD mice upregulated the incidence of diabetes, whereas co-transfer of CD4+ and CD8+ T cells from IL-27rα−/− NOD mice into Rag1−/− NOD mice did not induce diabetes, demonstrating that IL-27 signaling is essential for T1D development." (PMID 38566992, 2024).
HIV-1 infection (12 papers, 2010 to 2025). The type species of lentivirus and the etiologic agent of acquired immunodeficiency syndrome (AIDS). "The divergent effects of IL-27 on HIV-1 infection are associated with the dynamic of viral production by infected cells and dependent on cell-to-cell contact." (PMID 36602368, 2023). "In the case of HIV-1 infection, IFNα can itself be regulated by cytokines such as IL-27, and has been implicated in the antiviral actions of activator proteins such as tetherin and APOBEC3G." (PMID 20975956, 2010). "On the other hand, several in vitro studies have shown that IL-27 reduces HIV-1 infection in all types of HIV-1-target cells, such as peripheral blood mononuclear cells (PBMCs), CD4+ T cells, monocyte-derived macrophages, and dendritic cells (16, –, 20)." (PMID 36602368, 2023). "Here, we identify that IL-27 can produce opposing effects on HIV-1 replication in PBMCs and that the HIV-1 restriction factor BST-2/Tetherin is involved in both inhibitory and enhancing effects on HIV-1 infection induced by IL-27." (PMID 36602368, 2023). "Considering that IL-27 has been considered a potential therapeutic agent for HIV-1 infection, we aimed to provide additional findings on the ability of IL-27 to regulate HIV-1 infection in PBMCs." (PMID 36602368, 2023). "IL-27 favors HIV-1 infection when added 4 days later to infected cells and this effect involves BST-2/Tetherin." (PMID 36602368, 2023). "Recently, IL-27 signaling (IL-27 and its receptor) has been proposed to be involved in the pathogenesis of HIV-1 infection and immune reconstitution in infected individuals subjected to ART." (PMID 36851277, 2023). "Interleukin-27 (IL-27) is a cytokine that suppresses human immunodeficiency virus (HIV)-1 infection in macrophages and is considered as an immunotherapeutic reagent for infectious diseases." (PMID 34290273, 2021). "In this study, we investigated the impact of IL-27 in both autophagy induction and HIV-1 infection in macrophages." (PMID 34290273, 2021). "To date, there have been two relatively small studies investigating IL-27 levels in patients with HIV-1 infection." (PMID 24896094, 2014). "This potent anti-HIV activity of IL-27 against all major cell types infected with the virus has given credence to potentially using this cytokine as a novel therapeutic agent against HIV-1 infection." (PMID 24896094, 2014). "The aim of our study was to investigate the relationship between plasma IL-27 levels and HIV-1 infection in a large, well characterized cohort of HIV-1 infected patients." (PMID 24896094, 2014). "This demonstrated that IL-27, in a dose dependent manner, inhibited HIV-1 infection with ∼50% inhibition noted at a dose of 10 ng/ml and the maximal inhibition noted of approximately 90% at the highest dose used of 100 ng/ml." (PMID 23527130, 2013). "There have been two reported studies of the levels of IL-27 in plasma in patients with HIV-1 infection." (PMID 23527130, 2013). "As the goal was to eventually investigate the role of IL-27 in DCs with regard to HIV-1 infection, IL-27 treated DCs were also profiled and found to have similar levels of CD4, CCR5 and CXCR4 as iDCs or mDCs." (PMID 23527130, 2013). "In the current study, the aim was to investigate the effects of IL-27 on cis HIV-1 infection in DCs." (PMID 23527130, 2013). "Recently, IL-27 has been shown to be a potent inhibitor of HIV-1 infection in CD4+ T cells and macrophages." (PMID 23527130, 2013). "Given that the expression of BST-2/Tetherin may be regulated by IL-27, investigations are needed to elucidate whether this cytokine may also present contradictory roles during HIV-1 infection." (PMID 36602368, 2023). "Previous smaller studies have suggested that HIV-1 infection may alter IL-27 and influence HIV-1 pathogenesis." (PMID 24896094, 2014). "This is the largest study examining the levels of plasma IL-27 in HIV-1 infection." (PMID 24896094, 2014).